BCL2 (BCL2 apoptosis regulator)
Diseases named in the same sentence as BCL2 in open-access papers (continued):
Sharing a sentence is not in itself a finding about the gene and the disease.
cancer (continued). "BET family proteins perform transcription regulatory function under normal conditions, while in cancer, they regulate transcription of several oncogenes, such as c-Myc and Bcl-2." (PMID 25849938, 2015). "TOB1 antagonizes the v-akt murine thymoma viral oncogene (AKT) signaling and induces cancer cell apoptosis by activating BCL2-associated X (BAX) protein and inhibiting the BCL-2 and BCL-XL expressions." (PMID 26694352, 2015). "Fluorescent micrographs displayed an increase in Bcl-2 expression levels in carcinoma tissue exhibiting 95 % positivity in comparison to the control tissue (1 % positivity), LSILs (0 % positivity) and HSILs (2 % positivity)." (PMID 26474854, 2015). "Short interfering RNA (siRNA) targeted against anti-apoptotic Bcl-2 protein proved to knockdown its expression and trigger cancer cell death." (PMID 25229941, 2014). "The B-cell CLL/lymphoma-2 (Bcl-2) family of proteins are important regulators of the intrinsic pathway of apoptosis, and their interactions, driven by Bcl-2 homology (BH) domains, are of great interest in cancer research." (PMID 24481451, 2014). "Kuding tea significantly induced apoptosis in TCA8113 cancer cells (P<0.05) by upregulating Bax, caspase-3 and caspase-9 expression, and downregulating Bcl-2 expression." (PMID 24520272, 2014). "According to the topological properties of MSSPN and detailed mechanism dissection, we revealed the potentially significant roles of hsa05200 (pathway in cancer), four high-risk genes (IGF1R, IGF1, RAS, and BCL2), and associated miRSNPs in MG." (PMID 25118158, 2014). "For example, it was reported that constitutive or induced NF-κB activity in cancer cells makes them much more resistant to gemcitabine due to NF-κB controlled expression of several anti-apoptotic factors, such as Bcl2 or IAP family of proteins." (PMID 25402820, 2014). "We found considerable differences in Bcl-2 expression in patients with various macroscopic forms of cancers according to Bormann." (PMID 24741635, 2014). "Gossypol stimulates autophagy in multiple cancer types by disrupting the BCL-2/BECLIN1 complex as well as through a BECLIN-independent mechanism." (PMID 24824755, 2014). "The expression level of six differentially expressed mRNAs (CUL2, HIF1A, RET, JAK1, STAT1, and BCL2) in the cancer pathway and two of their nearby lncRNA pairs (RP11-124O11.2 and lincRNA-TMEM30B-1) was verified by real-time quantitative RT-PCR (qRT-PCR)." (PMID 24672800, 2014). "Expression of Beclin-1, PCNA, NET-1, Bcl-2, Bax, Survivin in cancer cells and CD34 in stromal microvessels were evaluated immunohistochemically in tissue microarrays comprising 103 cases of HCC and 57 matched adjacent nontumor liver tissues." (PMID 24885292, 2014). "Upregulation of anti-apoptotic proteins, including Bcl-2 and Mcl-1, or downregulation of pro-apoptotic Bax and Bak has been associated with resistance to TRAIL and recurrence of cancer." (PMID 24765133, 2014). "However, the association between BCL2 gene expression and cancer progression remains unclear." (PMID 25295115, 2014). "Interaction of MYD88 with Beclin1 reduces Beclin1 binding to Bcl-2, which leads to autophagy induction in cancer cells." (PMID 24527027, 2014). "Overexpression of the Bcl-2 protein is common in many human cancers, and contributes to their resistance to chemotherapy." (PMID 25019346, 2014). "Earlier studies had implicated a role for PI3K/Akt, epidermal growth factor receptor (EGFR) activation, and Bcl-2 in the survival of cancer cells under detachment." (PMID 25096718, 2014). "Bcl-2 is frequently overexpressed in many types of human cancers, including carcinomas, lymphomas, and leukemias." (PMID 25548562, 2014).
cancer (continued). "HeLa and UM-SCC-17B cancer cells were treated with anti-Bcl-2 particles followed by quantifying Bcl-2 mRNA and protein levels using qRT-PCR and western blotting, respectively." (PMID 25229941, 2014). "Higher expression of Bcl-2 was noted in cancer cells in patients with local lymph node involvement as compared to the metastasis-free patients (19/26; 73.1% versus 30/62; 48.4%, P < 0.05)." (PMID 24741635, 2014). "Its saponin macranthoside B has been shown to induce apoptosis in various kinds of cancer cells through activating the caspase cascades for intrinsic pathways and regulating the protein level of Bcl-2 and Bax, as well as Bax/Bcl-2 ratio." (PMID 25342273, 2014). "As the involvement of GSK-3β in the regulation of NF-κB activity is known to be significant for cancer cell growth, we investigated the levels of NF-κB pathway including Bcl-2 and survivin in LiCl treated SW480 cells." (PMID 25002914, 2014). "Our results are supported by other studies which shows that NSAIDs like selective COX-2 inhibitors NS-398 and SC-58125 can down regulate Bcl-2 and subsequently induce apoptosis in colon and prostrate cancer cell lines." (PMID 25663820, 2014). "In this study, our results suggested that canstatin promotes apoptosis both in endothelial cells and cancer cells via mitochondrial apoptotic pathway that included a reduction of Bcl-2 and Bcl-xl proteins, and an induction in Bax protein." (PMID 27919040, 2014). "When cancer cells receive apoptotic stimuli, such as in the cases of Epi alone or combined treatment with ASOs against pump resistance, the expression of BCL-2 would arise to resist apoptotic induction from Epi." (PMID 24637737, 2014). "Previous studies have shown that ABT-737, a BH3 mimetic, inhibited the pro-survival function of Bcl-2, Bcl-xL and Bcl-w, and induced apoptosis in a variety of cancer cell types." (PMID 25314317, 2014). "This cancer cell characteristic reflects, in part, a dysregulation of the balance between pro-apoptotic and anti-apoptotic BCL-2 proteins that regulate the intrinsic mitochondrial apoptotic pathway." (PMID 24824755, 2014). "In combination, these results suggest that emodin inhibits cancer cell growth via the regulation of the Bcl-2/Bax ratio and by its effect on the mitochondrial apoptosis pathway." (PMID 25187829, 2014). "For its greatest binding affinity and broadest binding pattern with Bcl-2 homology partners, we selected Bik as a cancer targeted therapeutic gene." (PMID 24637719, 2014). "These encouraging clinical data for ABT-263 and ABT-199 provide strong evidence that pharmacological targeting of critical anti-apoptotic Bcl-2 proteins has promise for the treatment of human cancers." (PMID 24901320, 2014). "Based on its ability to inhibit apoptosis, the B-cell lymphoma/leukemia 2 (Bcl-2) protein family has garnered the most attention as a promising therapeutic target in cancer." (PMID 24603326, 2014). "It does this, at least in part, by down-regulating PIWILI, cyclin B1, cyclin D1, bcl2 and up-regulating bax gene expression in several types of cancer cells, including A549." (PMID 25007054, 2014). "Increased expression of proapoptotic Bcl-2 protein contributes not only to the development of cancer but also to resistance against a wide variety of anticancer agents, such as cisplatin (DDP) and paclitaxel." (PMID 24999473, 2014).
cancer (continued). "A number of anticancer drugs trigger mitochondria-mediated apoptosis in cancer cells through the downregulation of Bcl-2/Bcl-xL or the upregulation of Bax/Bad/Bid." (PMID 24396481, 2014). "To better understand the role of LRPPRC in cancer development, we have previously reported that LRPPRC associates with mitochondria, interacts with Beclin 1 and Bcl-2 and form a ternary complex to maintain the Bcl-2 stability." (PMID 24722279, 2014). "Recent evidence suggests that Bcl-2 proteins also regulate cellular invasiveness and thus cancer metastasis." (PMID 25115399, 2014). "For example, overexpression of Bcl-w, Bcl-XL, or Bcl-2 in various cancer cell types increased the migratory and invasive potential of these cells, and consistently facilitated the metastasis of cancer cells in animal models." (PMID 25115399, 2014). "Bcl-2, the anti-apoptotic protein prototype, inhibits carcinogenesis and cancer cell growth both in vitro and in vivo." (PMID 25332145, 2014). "Bcl-2 is an anti-apoptotic protein, and the down-regulation of Bcl-2 is important for the induction of apoptosis by anti-cancer drugs." (PMID 24743574, 2014). "Previous studies linked the anticancer activity of NCTD to downregulation of Bcl-2, Bcl-xL and Mcl-1 since it was found that NCTD reduced the level of these antiapoptotic Bcl-2 family proteins in various cancer cells." (PMID 25022352, 2014). "Gossypol has been identified as a BH3-mimetic inhibitor of proapoptotic Bcl-2 family members, including Bcl-2, Bcl-xL, and Mcl-1, to induce apoptosis in cancer." (PMID 25180175, 2014). "Toward developing a highly potent and efficacious dual Bcl-2 and Bcl-xL inhibitor for cancer treatment, we have further optimized BM-1074 for its solubility and pharmacokinetic properties and this has led to BM-1197." (PMID 24901320, 2014). "From the dissection of hsa05200 (pathway in cancer), we revealed four high-risk genes (IGF1R, IGF1, RAS, and BCL2) to be MG risk genes and simultaneously showed they contained miRSNPs in their 3′UTR regions." (PMID 25118158, 2014). "Results show that pH-sensitive comb-like polymer complex anti-Bcl-2 siRNA forming “smart” nanoparticles that deliver their cargo into the cytoplasm of HeLa and UM-SCC-17B cancer cells causing Bcl-2 knockdown at the mRNA and protein levels." (PMID 25229941, 2014). "Several reports have explored the development of inhibitors of Bcl-2 protein as potential anti-cancer drugs." (PMID 24586269, 2014). "Others reported that antiapoptotic Bcl-2 proteins, e.g. Mcl-1, were rapidly and completely degraded in cancer cells treated with Obatoclax." (PMID 25192188, 2014). "For instance, the anti-apoptotic proteins SOCS3, BCL2, and BIRC5 are known to be implicated in a number of cancers and to contain putative miR-203 binding sites within their 3'UTRs." (PMID 25004126, 2014). "It has been therefore recognized that displacement of BH3-only proteins from Bcl-2/Bcl-XL or direct activation of BAX or BAD through BH3-mediated interaction is a major molecular mechanism for Gos-induced apoptosis in cancer cells." (PMID 25231749, 2014). "Over-production of Bcl-2/Bcl-xL proteins in cancer cells confers resistance to multiple chemotherapeutic agents whose primary mode of action is to trigger apoptosis." (PMID 24688837, 2014). "Study done by Chan and coworkers revealed that Bcl2 is expressed strongly in the surface epithelium of normal ovaries and benign and borderline ovarian tumors but weakly in the malignant tumors." (PMID 24864239, 2014). "In mouth cancer KB cells, Artemisia lavandulaefolia EO has been shown to decrease Bcl-2 protein level in dose dependent manner, which leads to apoptosis in cancer cells that is an important strategy to control cancer development and progression." (PMID 25003106, 2014). "An important breakthrough in the development of 4H-chromenes as anti-cancer agents was given by the discovery of HA 14-1, which targets the Bcl-2 protein." (PMID 25268519, 2014).
cancer (continued). "The over-expression of Bcl-2 has been observed in various cancers which contributes to drug resistance and enhances in-vivo cell survival while reduction in Bcl-2 expression increases drug sensitivity." (PMID 24586269, 2014). "Docking results on the active site of B-cell lymphoma 2 (Bcl-2) supported the experimental biological data and agreed well with previous in silico data for commonly used anti-cancer drugs." (PMID 24393539, 2014). "Drug resistance in cancer and MM has partly been assigned to elevated expression of the anti-apoptotic subfamily of Bcl-2 proteins." (PMID 25008202, 2014). "Elevation of Bcl-2 expression protects cancer cells from apoptosis, and the elevated expression of Bcl-2 and Bcl-xL has been frequently observed in a variety of cancers." (PMID 25333266, 2014). "Our findings can be explained by increased survival capacity acquired by cancer cells with high expression of antiapoptotic Bcl-2 or by possible changes in the protein profile in the course of cancer growth." (PMID 24741635, 2014). "The expression of survivin with other anti-apoptosis genes like Bcl-2 reduces apoptosis of cancer cells." (PMID 23755153, 2014). "More recently antimycins have been shown to be potent and selective inhibitors of the mitochondrial Bcl-2/Bcl-xL-related anti-apoptotic proteins which are over-produced by drug resistant cancer cells." (PMID 24688837, 2014). "Proapoptotic protein bax was upregulated after incubation with HBA, whereas the expression levels of antiapoptotic protein bcl2 was downregulated in all the three cancer cell lines." (PMID 25299784, 2014). "The results collectively indicate the potential of these particles to serve as a carrier for silencing Bcl-2 expression in cancer cells." (PMID 25229941, 2014). "For cancers in which BCL-2 and BCL-xL are co-expressed, the challenge lies in predicting which antiapoptotic protein is biologically more important for cell survival, and therefore, a more appropriate target for gene therapy." (PMID 24637737, 2014). "The B cell lymphoma/leukemia-2 gene (BCL2) and the Bcl2-associated X protein gene (BAX) are an oncogene and a cancer suppressor gene, respectively." (PMID 24459422, 2013). "Growing evidence suggests that Bcl-w enhances not only survivability as a pro-survival member of the Bcl-2 (B cell lymphoma-2) protein family, but also the migratory and invasive potentials of cancer cells as an additional function." (PMID 23826359, 2013). "Anti-apoptotic modulating therapy is a promising strategy for cancer drug discovery and many groups are investigating the effects of Bcl-2, Bcl-xL or XIAP inhibition using antisense oligonucleotides and small mimetic molecules." (PMID 24688727, 2013). "Conversely, overexpression of antiapoptotic Bcl-2 protein inhibited both cytochrome c release and apoptosis of aspirin-treated cancer cells." (PMID 23983899, 2013). "This binding protects the anti-apoptotic Bcl-2 from degradation, resulting in stabilization of Bcl2 mRNA, which subsequently promotes the cancer cells to overproduce Bcl2 and avoid apoptosis." (PMID 25057429, 2013). "Further studies are needed to elucidate the mechanism of RAD-inhibited Bcl-2 protein level in cancer cells." (PMID 23840275, 2013). "In the group treated with U14 cells (cancer-induced group), the Bax, Bcl-2, caspase-3 and caspase-9 genes demonstrated significant changes." (PMID 23599733, 2013).
cancer (continued). "So far, only few is known about a potential commitment of antiapoptotic Bcl-2 proteins on migration and invasiveness of cancer cells." (PMID 24098503, 2013). "The ability of NSAIDs to activate caspases largely explains the profound influence they have on Bcl-2 proteins such as Bax, Bid, and Bcl-2, the expression and cellular distribution of which can be greatly altered by NSAIDs to mediate apoptosis in cancer cells." (PMID 23983899, 2013). "The B-cell CLL/lymphoma 2 (BCL2) is an anti-apoptotic factor which is overexpressed in several human cancers, where it contributes to resistance to treatment by conventional anticancer approaches." (PMID 24108400, 2013). "Our results show that exogenous ChoPlas treatment can reduce the expression of Bcl-2, an indication that exogenous natural ChoPlas affects cancer cell proliferation by promoting cancer cell apoptosis." (PMID 24143228, 2013). "The Bcl-2/Bcl-xL family of proteins are over-produced in cancer cells that are resistant to apoptosis-inducing chemotherapy agents, so antimycins have great potential as anticancer drugs used in combination with existing chemotherapeutics." (PMID 24367419, 2013). "In bcl-2-positive cancer cells (cancer cells expressing bcl-2), taxol induces the phosphorylation of bcl-2 and programmed cell death thereafter." (PMID 28809320, 2013). "Bcl-2 and Bcl-xL proteins are overexpressed in a variety of human cancers, and are important members of anti-apoptotic proteins family." (PMID 23828460, 2013). "Small molecule inhibitors and peptides (i. e., BH3 mimetics) as well as antisense and gene therapy strategies have been widely used to counteract the antiapoptotic activity of BCL2 in different cancer models." (PMID 24108400, 2013). "In many cancer cell types, Bcl-2 and Bcl-XL were overexpressed, which contributed to the resistance of cancer cells to chemotherapeutic agents and radiation therapy." (PMID 23700426, 2013). "Previous studies have indicated that Bcl-2 is highly overexpressed in some cancers and enhances cancer cell survival." (PMID 24143228, 2013). "More importantly, increasing the incubation time from 6 to 24 hours led to the increase of Bax/Bcl-2 ratio, which is an important apoptosis inducer indicator in cancer cells." (PMID 23509778, 2013). "Small molecules that inhibit pro-survival Bcl-2 proteins in cancer cells counteract chemoresistance and cure cancer in a high percentage of mice." (PMID 23441221, 2013). "Regulation of bcl-2 on mRNA as well as protein level has attracted increasing attention over the last years and is frequently an obstacle on cancer treatment." (PMID 23305559, 2013). "Both SCLC and pulmonary carcinoid tumors are characterized by having high expression of Bcl-2 expression and the chemotherapy resistance commonly seen in these types of cancer suggests dependence on anti-apoptotic proteins." (PMID 24688727, 2013). "Cancers with high level of Bcl-2 or Bcl-xL are also resistant to a wide spectrum of chemotherapeutic agents and radiation therapy." (PMID 24050266, 2013). "Since DNA methylation was usually accompanied by gene silencing, the role of BCL2 in the development and progression of cancer was complicated and further studies are warranted." (PMID 23599765, 2013). "Collectively, these data convincingly suggest that JY-1-106 is a pan-Bcl-2 inhibitor capable of antagonizing the two distinct subclasses of anti-apoptotic proteins, Bcl-2/xL and Mcl-1, both of which are critical for cancer cell survival." (PMID 23680104, 2013). "Overexpressed Bcl-2 in a variety of cancers contributes to cancer cell survival through direct inhibition of apoptosis." (PMID 27335822, 2013). "In our study, the antiovarian cancer of PGPIPN was mainly through the induction of apoptosis mediated by down-regulation of BCL2." (PMID 23593287, 2013).